CDC27 (cell division cycle 27)
Diseases named in the same sentence as CDC27 in open-access papers (continued):
Sharing a sentence is not in itself a finding about the gene and the disease.
CDC27 also shares sentences with these, for which no sentence is quoted: acute myeloid leukemia (1 paper); colorectal (1); congenital heart disease (1); diabetes (1); endometrial cancer (1); glioblastoma (1); idiopathic pulmonary fibrosis (1); immune disorders (1); infective endocarditis (1); Infertility (1); liver cancer (1); migraine (1); myopia (1); neurological diseases (1); osteosarcoma (1); pyomyositis (1); renal carcinoma (1); testicular germ cell tumor (1); triple-negative breast carcinoma (1); Vertigo (1); α-thalassemia (1).